PIEZO2 (piezo type mechanosensitive ion channel component 2)
Diseases named in the same sentence as PIEZO2 in open-access papers (continued):
Sharing a sentence is not in itself a finding about the gene and the disease.
channelopathy (continued). "It is important to note again that one suggested consequence of Piezo2 channelopathy is the leakage of subthreshold imbalanced Ca2+ currents when Piezo2 should be intact and inactivated in a hyperexcited state." (PMID 36983813, 2023). "The disruption in corneal neural regeneration is theorized to be initiated by chronic Piezo2 channelopathy-induced impaired Piezo2-Piezo1 crosstalk, hence the constantly activated transcription process and disrupted, but “kept alive”, wound healing." (PMID 37895134, 2023). "In summary, it seems that chronic spinal facet joint Piezo2 channelopathy and the resultant impaired Piezo2-Piezo1 crosstalk will eventually lead to IL-17-induced entheseal Piezo1 upregulation in a feed-forward, low-grade inflammatory manner in AS." (PMID 37895134, 2023). "The current manuscript postulates that Piezo2 channelopathy is a principal transcription activator in proprioceptive terminals." (PMID 36983813, 2023). "The mechano part of the microinjury is proposed to be a Piezo2 channelopathy, while the metabo-energetic part is the impairment of the glutamate vesicular release." (PMID 36144262, 2022). "Piezo2 channelopathy also means the impaired cross-talking between Piezo2 and Peizo1, as was suggested in DED." (PMID 36233237, 2022). "Accordingly, the current authors also propose that C-fiber contribution is needed for the evolution of NCP beyond the Piezo2 channelopathy." (PMID 35507012, 2022). "The current authors suggest that unwanted Piezo Ca2+ currents due to impaired gating of Piezo2 channelopathy opens the gate to pain sensation, but C-fiber contribution is essential for transmitting nociceptive information in NCP." (PMID 35507012, 2022). "This manuscript only proposes the Piezo2 channelopathy as the critical gateway to pathophysiology, and certainly does not exclude the possible involvement of other ion channels and receptors, although only in secondary or tertiary fashion." (PMID 36233237, 2022). "Even more precisely, the cardiac parasympathetic activity after an ASR, which is a full parasympathetic withdrawal, cannot return until the Piezo2 channelopathy is functionally regenerated or becomes unleaky in the hyperexcited states." (PMID 36139045, 2022). "As a result, this acquired Piezo2 channelopathy could induce a somatosensory switch/miswiring and resultant sensory mismatch, exaggerated quadriceps contractions and delayed static phase firing encoding that puts greater load on the ACL." (PMID 41441398, 2025). "Moreover, Piezo2 channelopathy likely promotes diminishing HSF1 function in the hippocampus in the presence of the identified HSF1 variant." (PMID 41155507, 2025). "However, it is proposed that the underlying pathomechanism is again initiated in the proprioceptive terminals of the muscle spindle due to an irreversible autonomously acquired Piezo2 channelopathy." (PMID 40076941, 2025). "It is important to note that mild TBI is suggested to be an analogous bi-phasic non-contact injury mechanism, similar to DOMS, where the primary damage may also involve an acquired proprioceptive neuron terminal Piezo2 channelopathy." (PMID 40863771, 2025). "Even more importantly, the impaired low-frequency Schottky semiconductor barrier diode-like function of Piezo2, as a result of Piezo2 channelopathy, may fail to modulate these ROS-dependent mitochondrial high-frequency oscillations." (PMID 40863771, 2025). "Since Piezo2 channelopathy is suggested to be a principal transcription activator, it may not only impact adult hippocampal neurogenesis, but might activate non-coding heat shock RNA-1 (HSR1) in order to activate HSF1." (PMID 41155507, 2025). "Later, even the microdamage of an ion channel was hypothesized for the initiation of the primary damage of this bi-phasic non-contact injury mechanism, namely in the form of an acquired Piezo2 channelopathy on the proprioceptive somatosensory nerve terminals." (PMID 41441398, 2025).
channelopathy (continued). "Multiple studies have suggested that Piezo2 channelopathy may contribute to autoimmune disease pathogenesis." (PMID 40873759, 2025). "Hence, Piezo2 channelopathy not only contributes to cancer initiation and impaired circadian regulation, including the proposed hippocampal ultradian clock, but also to proliferation and metastasis." (PMID 40806290, 2025). "More specifically, two states of Piezo2 may prevail under allostatic stress, namely, inactivated intact Piezo2 and the acquired channelopathy of Piezo2 due to the prolonged eccentric nature of DOMS-inducing exercise." (PMID 40863771, 2025). "Moreover, not only Piezo2 initiated crosstalk between proprioceptive Type Ia terminal and hippocampus is impaired according to Piezo2 channelopathy theory, but disrupts the long suspected Piezo2-Piezo1 cross-talk in ALS as well." (PMID 41155507, 2025). "This Piezo2 channelopathy may also disrupt the ultrafast proton-based oscillatory signaling to motor neurons through vesicular transporter 1 (VGLUT1) and to the hippocampus through VGLUT2." (PMID 41155507, 2025). "Hence, Piezo2 channelopathy is not only a proprioceptive switch or miswiring mechanism, but also a metabolic switch, as was indicated by Sonkodi, in DOMS and ALS." (PMID 40076941, 2025). "Moreover, this acquired Piezo2 channelopathy also proposed to impair the crosstalk between Piezo2 and Piezo1 channels in the given compartmental micromilieu and the crosstalk between Piezo2 and Piezo2 channels beyond the given compartments." (PMID 41155507, 2025). "Anaerobic exercise substantially delays the return of parasympathetic tone, or autonomic control, compared to aerobic exercise, while strenuous exercise delays this return by two days, which is suggested to overlap with the time window for Piezo2 channelopathy." (PMID 40863771, 2025). "Interestingly, TMEM120A contributes to leakage currents, and part of the Piezo2 channelopathy theory suggests that Piezo2 microdamage induces subthreshold leakage currents." (PMID 40076941, 2025). "This acquired channelopathy may also mean an impaired crosstalk between Piezo2 and Piezo1 channels within the affected compartment." (PMID 38534336, 2024). "Since MyoD is a transcription factor, the (functional) loss of the auxiliary connection of MyoD family inhibitor proteins could represent one explanation of the proposed principal transcription activator function of Piezo2 channelopathy." (PMID 38534336, 2024). "However, it is important to note again that these mechanisms are severely and progressively impaired due to the theorized irreversibility of Piezo2 channelopathy and resultant lost crosstalk between Piezo2 and Piezo1 in the affected compartments of ALS." (PMID 38534336, 2024). "DOMS may interfere with this hippocampal theta rhythm synchronization due to acute Piezo2 channelopathy and functional syndecan-3 depletion." (PMID 38534336, 2024). "In support, PIEZO2 channelopathy-derived impaired PIEZO2-PIEZO1 crosstalk downregulates PIEZO1 on certain cells, like dendritic cells, and upregulates PIEZO1 on other cells, like satellite/astrocyte cells within the affected compartments or organs with blood barriers." (PMID 39682086, 2024). "Since PIEZO2 channelopathy is also suggested to be a principal transcription activator, underlying genetic variants could be revealed and could have relevance for individual differences." (PMID 39519393, 2024). "However, the Piezo2–Piezo1 crosstalk is suggested to be progressively blunt due to irreversible proprioceptive Piezo2 channelopathy in ALS." (PMID 38534336, 2024). "An important consideration is that the impairment of this cross-talk could arise from both directions, from PIEZO1 channelopathy and PIEZO2 channelopathy as well." (PMID 39519393, 2024). "Furthermore, the theory of Piezo2 channelopathy also entails the impairment of the glutamate vesicular release machinery." (PMID 38534336, 2024).
channelopathy (continued). "Accordingly, excessively prolonged mechanotransduction under allostasis could bear relevance in the evolvement of Piezo2 channelopathy due to the altered cell surface charge of syndecan-3 by shedding or charge-atltering variants of the SDC3 gene." (PMID 38534336, 2024). "Most likely, Piezo1 channelopathy is also a transcription activator, and it is also important to note that Piezo1 channelopathy could also induce Piezo2 channelopathy under prolonged stress-induced mechanotransduction." (PMID 38534336, 2024). "Moreover, Piezo2 channelopathy is suggested to disrupt Piezo2–Piezo1 crosstalk within a Piezo2 microinjured compartmental micromilieu." (PMID 38534336, 2024). "Moreover, PIEZO2 channelopathy impairs PIEZO2-PIEZO1 crosstalk within a compartmental micromilieu, and astrocytes contain PIEZO1 even in the hippocampus." (PMID 39682086, 2024). "This Piezo2 channelopathy is proposed to be a principal transcription activator; hence, it could reveal the underlying genetic variants that become more apparent during the time window of this ion channel microinjury." (PMID 38534336, 2024). "According to the Piezo2 channelopathy theory, the membrane lipids and cholesterol surrounding Piezo2 could be depleted during excessively prolonged mechanostransduction under allostasis." (PMID 38534336, 2024). "The theorized peripheral intrafusal Piezo2 channelopathy-induced transient disruption of Piezo1–Piezo2 crosstalk and NMDA activation in DOMS could be the reason why orthostasis may be impaired." (PMID 37999426, 2023). "Furthermore, acid-sensing ion channel 3 (ASIC3) is also known to activate WDR neurons in the spinal dorsal horn, and ASIC3 activation in intrafusal type II fibers is proposed in relation to type Ia proprioceptive terminal Piezo2 channelopathy in DOMS." (PMID 36983813, 2023). "The current authors propose that Piezo2 channelopathy-induced K2P channel activation through TASK1 channels on the spinal level could promote one pathomechanistic link between autoimmune diseases and DE." (PMID 37108693, 2023). "Correspondingly, it was recently postulated that the channelopathy of Piezo2 could impair the Piezo system or, more precisely, the delicate crosstalk between Piezo1 and Piezo2 channels, which could lead to impaired orthostasis and proprioception." (PMID 37108199, 2023). "The current authors interpreted and showed earlier that the autologous Piezo2 channelopathy-induced impaired Piezo2-Piezo1 crosstalk could be the reason why neural regeneration of the cornea is disrupted in DED secondary to RA and SLE." (PMID 37895134, 2023). "Recently it was theorized that the autologous channelopathy of Piezo2 at corneal somatosensory terminals contributing to proprioception could be the primary damage of a quad-phasic non-contact injury mechanism in DED and in autoimmune conditions." (PMID 37445856, 2023). "The difference could be that Piezo2 channelopathy could be a more complex one and induces NMDA and Na+-persistent inward currents (PIC), as hinted earlier, while Nav1.1 or Nav1.6 channelopathies could evoke only NaPICs." (PMID 36983813, 2023). "This Piezo2 channelopathy could be one ignitor of the so-called neural circuit-based inflammatory reflex, with a first line disbalanced activated NKT cell response." (PMID 37895134, 2023). "However, chronic Piezo2 channelopathy not only keeps transcription activated and wound healing unfinished, but is also postulated to disrupt the crosstalk with Piezo1 of peripheral cells." (PMID 37445856, 2023). "Suitably, terminal arbor degeneration is also theorized to evolve due to Piezo2 channelopathy, as Piezo2 channelopathy could enhance the deregulation of the autonomic nervous system." (PMID 37895134, 2023).
channelopathy (continued). "According to this Piezo2 channelopathy theory, Piezo2 ion channels should be considered as homeostatic gatekeepers of peripheral sensory neuron terminals in a compartmental micro-milieu, whereas Piezo1 ion channels are the homeostatic gatekeepers of the surrounding peripheral cells." (PMID 37895134, 2023). "The current author suggests that the proposed miswiring could have two sources, namely Piezo2 channelopathy and Nav1.1 channelopathy." (PMID 36983813, 2023). "The current authors suggest that this disruption in regeneration of nerve fibers could have been the result of impaired crosstalk between corneal somatosensory-terminal Piezo2 and peripheral-cell Piezo1 due to chronic Piezo2 channelopathy." (PMID 37108693, 2023). "Even more importantly, it is theorized that an inadequate mitochondrial supply and dysfunctional mitochondria could lead to Piezo2 channelopathy at the proprioceptive terminals." (PMID 36983813, 2023). "It is hypothesized that mitochondria could become dysfunctional under unaccustomed or strenuous loading of eccentric contraction-induced ASR time window, leading to Piezo2 channelopathy." (PMID 36983813, 2023). "The authors of this manuscript propose that the observed corneal sensory morphology could have been the result of impaired crosstalk between corneal somatosensory-terminal Piezo2 and peripheral-cell Piezo1 due to chronic Piezo2 channelopathy." (PMID 37108693, 2023). "Moreover, the same Piezo2 channelopathy also disrupts the Piezo2–Piezo1 crosstalk; therefore, if the underlying genetic variants and cell type-specific noncoding DNA mutations impede proper regeneration, then the wound healing process is kept alive." (PMID 37445856, 2023). "However, the current authors suggest that the initial corneal barrier disruption and immune cell migration are due to the Piezo2 channelopathy-induced impaired Piezo2-Piezo1 cross-talk." (PMID 37895134, 2023). "Prolonged or abrupt static compression is indeed implicated in the Piezo2 channelopathy mechanism of the noncontact compression axonopathy theory." (PMID 37108693, 2023). "The authors of this manuscript suggest that Piezo2 channelopathy and the resultant unwanted subthreshold Ca2+ currents could propel the pathomechanism towards enthesis, not to mention contributing to pain sensation and even to neuropathic pain." (PMID 37895134, 2023). "It is important to understand the pathomechanism of the Piezo2 channelopathy theory in order to understand the pathways that could lead to this principal microinjury gateway directly or indirectly." (PMID 36983813, 2023). "A problem could arise when underlying genetic mutations or environmental risk factors impede the due closure of this activated transcription process, resulting in an unfinished healing process and chronic Piezo2 channelopathy instead of a transient process." (PMID 37108693, 2023). "In brief, the pathological hyperexcitation of the proprioceptive afferent terminals induces ROS production in association with neuroinflammation and neural activation in the spinal cord due to this proposed transient Piezo2 channelopathy, in addition to ROS generation in muscle cells." (PMID 36983813, 2023). "Not to mention that Piezo2 channelopathy is also suggested to be associated with impaired crosstalking between Piezo1 and Piezo2, beyond being a principal transcription activator." (PMID 37445856, 2023). "The current authors translate these findings that spinal-cord neuroinflammation in DOMS could be the consequence of the Piezo2 channelopathy and the resultant central synaptic disconnection of the same proprioceptor from motor neurons." (PMID 35736014, 2022). "Piezo2 channelopathy could result in the imbalanced control of Piezo1 on keratinocytes in a clustered manner, leading to dysregulated keratinocyte proliferation and differentiation." (PMID 36233237, 2022).
channelopathy (continued). "The actual microdamage that could lead to this Type Ia impairment is suggested to be energy-depleted-mitochondria-induced dysfunctional glutamate vesicular release and Piezo2 channelopathy." (PMID 35736014, 2022). "The theory highlighted glutamate and the COX-1–PGE2 excitatory pathways that could lead to pathological hyperexcitation, impairment of glutamate vesicular release, and Piezo2 channelopathy on Type Ia fibers in the primary damage phase of DOMS." (PMID 36144262, 2022). "Later, it was hypothesized that the locus of this causal neuron terminal microdamage is on Piezo2 ion channels, in the form of a transient Piezo2 channelopathy." (PMID 35736014, 2022). "Furthermore, the suggested proprioceptive Piezo2 channelopathy-induced NMDA receptor activation opens several memory pathways at the central terminal on the spinal dorsal horn, such as pain memory, inflammation, working and episodic memory." (PMID 36139045, 2022). "However, when Piezo2 channelopathy may become irreversible in ALS, the activated NF-κB pathway by TLR4/Myd88 signaling keeps on propelling the neuroinflammation in the CNS with non-resolving progressive impairment of the proprioceptive circuitry." (PMID 41155507, 2025). "It has been also hypothesized that Piezo2 channelopathy could be autonomously acquired, not only inherited or genetically engineered, in an acute transient form in the primary damage phase of delayed-onset muscle soreness (DOMS) by fatiguing forced lengthening contractions under allostatic stress." (PMID 39941012, 2025). "However, this negative homeostatic regulation is hypothesized to be disrupted by the Piezo2 channelopathy-induced DOMS effect." (PMID 40137805, 2025). "However, the principal gate control of pain mechanism may reside further upstream on Type Ia proprioceptive terminals in the case of DOMS, where the acquired channelopathy of Piezo2 may lead to a neural switch and pain evolvement." (PMID 40863771, 2025). "Accordingly, abrupt/ultrafast reactiveness to perturbations of Piezo2 may come from quantum mechanical properties, where Piezo2 initiates the ultrafast proton-based long-range signaling, but acquired Piezo2 channelopathy may impair this ultrafast capability, leading to increased injury risk." (PMID 41441398, 2025). "However, Piezo2 channelopathy may impair this finely regulated Piezo2-initiated ultrafast ultradian hippocampal organization due to over-excessive axial compression forces." (PMID 41441398, 2025). "Hence, SampEn may represent the Piezo2 modulating capability of excess entropy, and Piezo2 channelopathy, or proton reversal, impairs this modulating capability." (PMID 40863771, 2025). "Therefore, combined TES and PES treatment seems to reinvigorate Piezo2 from its channelopathy and the resultant proton reversal by giving rise to proper proton conduction not only along the muscle–brain axis but also along the damaged bi-compartmental communication structures of Piezo2 ion channels." (PMID 40863771, 2025). "Therefore, activated ASIC3 in intrafusal Type II fibers and, later, in Type III fibers, could also contribute to the initial activation of the WDR neurons due to the autonomously acquired Piezo2 channelopathy-induced proprioceptive switch." (PMID 40076941, 2025). "Moreover, Piezo2 channelopathy-induced impaired ultrafast proton-based signaling through vesicular glutamate transporter 1 (VGLUT1) may underpin this impaired input." (PMID 41155507, 2025). "Moreover, the charge-altering variants of syndecan-3-encoding SDC3 gene may have special relevance to the disruption of this crosstalk during the aging process, since Piezo2 channelopathy is theorized to be also subject to mitochondrial dysfunctionality." (PMID 38534336, 2024). "Consequently, the suggested Piezo2 channelopathy may lead to excessive proton leak, glutamate excitotoxicity, acidosis, and intrafusal Type II afferent sensitization through ASIC3." (PMID 38534336, 2024).